BRCA1 (BRCA1 DNA repair associated)
Diseases named in the same sentence as BRCA1 in open-access papers (continued):
Sharing a sentence is not in itself a finding about the gene and the disease.
ovarian carcinoma (continued). "Ovarian cancers in patients with germline mutations in the BRCA1 or BRCA2 genes are more sensitive to DNA damaging agents such as cisplatin." (PMID 28423708, 2017). "To date, a limited number of BRCA1/2 germline mutations have been reported in hereditary breast and/or ovarian cancer in the Moroccan population." (PMID 28577564, 2017). "The current literature provides data on the up-regulation of miRNAs, such as miRNA-9, miRNA-146a, miRNA-182 miRNA-218, miRNA-638 and is association with treatment response in breast and ovarian cancer when associated with the BRCA1 mutation." (PMID 29021870, 2017). "Approximately 15-20% of ovarian cancers are attributable to germline BRCA1/2 mutations resulting in defects in the homologous recombination (HR) pathway." (PMID 29137324, 2017). "The PARP inhibitor olaparib (LynparzaTM, also known as AZD2281) is approved for ovarian cancer with germline BRCA1/2 mutations in the US and EU, and for somatic BRCA1/2 mutations in the EU only." (PMID 28525389, 2017). "Risk-reducing salpingo-oophorectomy (RRSO) reduces ovarian cancer risk in BRCA1/2 mutation carriers." (PMID 28060958, 2017). "Inhibiting PARP1 in HR-deficient cells, such as the BRCA1- or 2-mutant breast and ovarian cancers, leads to an accumulation of DNA damage from replication fork collapse and ultimately cell death." (PMID 28756516, 2017). "For the treatment of ovarian cancers, bearing HR DNA repair defects because of BRCA1/2 mutations, the FDA has approved olaparib, an inhibitor of the repair enzyme Poly(ADP-ribose) polymerase (PARP)." (PMID 28653990, 2017). "This worldwide frequency is comparable to the overall prevalence of BRCA1/2 mutations among ovarian cancer patients in Polish population, estimating at ~15% for germline and ~4% for somatic variants." (PMID 29254167, 2017). "Evidence of association with ovarian cancer risk (p < 10−2) was observed for six SNPs in BRCA1 mutation carriers and three SNPs in BRCA2 mutation carriers." (PMID 27796716, 2017). "Response rates of 30% have been reported in a subsequent phase II studies conducted in refractory advanced BRCA-mutant ovarian cancer, suggesting BRCA1-2 mutations as potential predictive biomarkers for clinical use." (PMID 28055979, 2017). "In total, about one-fifth of ovarian cancer patients carry a pathogenic variant in the BRCA1/2 gene." (PMID 29254167, 2017). "Olaparib has activity against ovarian cancer in women with germline mutations in BRCA1 or BRCA2, consistent with the synthetic lethality mechanism of PARP inhibitors." (PMID 28525389, 2017). "As previously stated, BRCA1/2-associated ovarian cancer has multiple distinct features affecting age at diagnosis, disease distribution, chemosensitivity and survival." (PMID 28250960, 2017). "Women who carry BRCA1 mutations are at a significantly increased risk for ovarian cancer and high prevalence of OEIs have been found in prophylactically removed ovaries of BRCA mutation carriers." (PMID 28270171, 2017). "Here, we assessed circulating tumor DNA (ctDNA) from 121 patients with ovarian cancer for BRCA1/2 mutational analysis by next generation sequencing." (PMID 29254167, 2017). "These inhibitors have been described as a powerful therapy for patients with hereditary breast or ovarian cancer containing mutations in the BRCA-1 and BRCA-2 genes that are essential for repairing DNA lesions by the homologous recombination pathway." (PMID 29073231, 2017). "Following the identification of a BRCA1/BRCA2 mutation shortly after ovarian cancer diagnosis, the initial focus is often placed on treatment implications for the woman and risks to her relatives." (PMID 28780755, 2017). "Oncomine®BRCA1/2 Panel accurately detects pathogenic BRCA1/2 variants in patients with breast and/or ovarian cancer, so is feasible for use in cancer genome research and diagnostic purposes in a clinical setting." (PMID 29383094, 2017).
ovarian carcinoma (continued). "Advances in the understanding of the molecular biology of epithelial ovarian cancer, and the impact of BRCA1 and BRCA2 gene mutations on cellular DNA repair pathways, has led to the development of PARP inhibitors, an exciting new class of targeted therapy." (PMID 28665051, 2017). "A meta-analysis investigating the ovarian cancer risk of 8139 patients with BRCA1 and BRCA2 mutations was published in 2003 and associated with the citation peak in 2004." (PMID 28086974, 2017). "The overall frequency of germline and somatic BRCA1/2 mutations found in the plasma from ovarian cancer patients was 19% and 6.6%, respectively that is consistent with the previous studies." (PMID 29254167, 2017). "This study highlighted the need to verify CNVs in vitro, but also provides evidence that experimentally validated CNVs (with plausible biological consequences) can modify risk of breast or ovarian cancer in BRCA1 pathogenic variant carriers." (PMID 28145423, 2017). "We tested 147 buffy coat samples from patients with breast and/or ovarian cancer to detect germline variants by next-generation sequencing using the IonAmpliSeqTM BRCA1/2 Panel or Oncomine®BRCA1/2 Panel." (PMID 29383094, 2017). "In her two op-eds, she explained that − as a carrier of the BRCA1 gene mutation − preventive surgery was the best way to lower her heightened risk of developing breast and ovarian cancer." (PMID 29278246, 2017). "One of the positive outcomes of BRCA1/2 genetic cancer testing is that when a pathogenic germline variant has been identified, surveillance and preventive strategies can reduce breast/ovarian cancer incidence and increase life expectancy." (PMID 28570656, 2017). "It is now known that a significant proportion of the genetic risk of developing breast and ovarian cancer is due to germline mutations in the genes BRCA1 and BRCA2." (PMID 26574041, 2017). "Germline, heterozygous mutations in BRCA1 confer high risk of breast and ovarian cancer development in an autosomal dominant fashion." (PMID 28398198, 2017). "Several other PARP inhibitors are currently at different stages of clinical development in patients with BRCA1/2 mutation ovarian cancer." (PMID 28454085, 2017). "This article reviews reported relationships between various miRNAs and the response to cytostatic drugs in the treatment of breast and ovarian cancer associated with BRCA1 mutations." (PMID 29021870, 2017). "Separate analyses were performed to evaluate the cumulative risk of ovarian cancer by age 45 years in first-degree relatives of BRCA1/2 mutation carriers." (PMID 28680148, 2017). "The Oncomine®BRCA1/2 Panel detected 21 pathogenic germline variants in 147 patients with breast and/or ovarian cancer, of which 20 were detected by the previously-launched Ion AmpliSeqTM BRCA1/2 Panel, except for one frameshift mutation." (PMID 29383094, 2017). "In our studies, mean HE4 levels were assessed in a group of patients at the highest risk of ovarian cancer, that is, in patients diagnosed with BRCA1 gene mutation." (PMID 28182133, 2017). "The clinical activity of olaparib in patients with advanced germline BRCA1/2 mutation ovarian cancer has been assessed in a number of phase I/II trials." (PMID 28454085, 2017). "The pattern of serum HE4 levels in pre- and postmenopausal patients is similar, with the highest medians in the ovarian cancer and endometrial cancer groups and the lowest medians in the BRCA1 mutation groups." (PMID 28182133, 2017). "The strongest association with ovarian cancer risk in BRCA1 carriers was observed for rs12025623 located at 1p36.12 (p = 7 × 10−3) in an intron of the ALPL gene." (PMID 27796716, 2017). "Recently, more and more patients with ovarian cancer have been receiving genetic counseling and testing, including BRCA1/2 and the other heterologous recombinant deficient (HRD) genes, because of the development of PAPP inhibitors." (PMID 29163180, 2017).
ovarian carcinoma (continued). "Approximately 5% of breast and 20% of ovarian cancers arise in women carrying heterozygous germline mutations in the cancer susceptibility genes BRCA1 or BRCA21." (PMID 28831036, 2017). "Pathogenic BRCA1/2 germline mutations confer high risks of breast and ovarian cancer to women of European ancestry." (PMID 28680148, 2017). "Analyses identified several putative CNVs overlapping gene regions associated with risk of breast or ovarian cancer for BRCA1 pathogenic variant carriers and a requirement for validation in larger studies." (PMID 28145423, 2017). "Women aged 25–55 years with germline BRCA1/2 mutations who were unaffected with breast or ovarian cancer were recruited through research registries at five clinics and a patient advocacy group." (PMID 28624978, 2017). "Olaparib is currently clinically employed in ovarian cancers harboring BRCA1/2 deficiencies, and has also begun to show promise in BRCA1/2-deficient chemoresistant, metastatic breast and prostate cancers." (PMID 29104272, 2017). "When combined with mutations in genes that cause hereditary breast and ovarian cancer such as BRCA1, BRCA2, PALB2 and RAD51C, depletion of Rad52 is shown to be synthetically lethal." (PMID 28722656, 2017). "The finding that niraparib decreased replication fork restart and increased genomic instability is consistent with the molecular mechanism of synthetic lethality in PARP1 inhibition in BRCA1 and 2-deficient breast and ovarian cancers." (PMID 28756516, 2017). "Accurate estimates of the risk of breast and ovarian cancers for BRCA1/2 mutation carriers are crucial for genetic counselling." (PMID 28680148, 2017). "BRCA1 was originally identified based on linkage to genetic susceptibility in breast and ovarian cancers." (PMID 28525389, 2017). "A study of 3765 patients in the U.S. with epithelial ovarian cancer found that only 50% of patients meeting substantial-risk criteria for BRCA1/2 mutations were referred to genetics." (PMID 28250960, 2017). "Olaparib is an oral PARP1 inhibitor that has been recently approved for the treatment of relapsed ovarian cancer that harbors BRCA1 or 2 mutations." (PMID 28756516, 2017). "Female BRCA1/2-mutation carriers have a cumulative lifetime risk of BC up to 60–80%, and an increased risk of ovarian cancer (OC) up to 20–60% for BRCA1 and 5–20% for BRCA2." (PMID 27966054, 2017). "This is similar to the inherited HR deficiencies, such as the BRCA1 and 2 mutations, that lead to breast and ovarian cancers." (PMID 28756516, 2017). "As an example, we previously identified that the single nucleotide polimorphism “rs2304277”, located 1.8Kb downstream the 3′-untranslated region (UTR) of OGG1 gene, was associated with an increased ovarian cancer risk for BRCA1 mutation carriers." (PMID 29383107, 2017). "Several publications have reported the presence of somatic BRCA1/2 mutations in ovarian cancer, highlighting that both germline and somatic mutations in HRD genes can result in ovarian cancer." (PMID 28250960, 2017). "Olaparib and niraparib are both orally active PARP1 inhibitors that are effective in the treatment of ovarian cancers with BRCA1 and BRCA2 mutations." (PMID 28756516, 2017). "This is done to avoid missing them as a result of the germline subtraction performed during the tumor analysis (i.e., a potential BRCA1 loss of function mutation present both in an ovarian cancer and in the germline sequence)." (PMID 28717660, 2017). "Until recently our knowledge of a genetic contribution to ovarian cancer focused almost exclusively on mutations in the BRCA1/2 genes." (PMID 28250960, 2017). "Recent literature suggests that up to 24% of ovarian cancers are associated with germline mutations, and of these, 29% have mutations in genes other than BRCA1 or BRCA2." (PMID 28250960, 2017). "Questions on the approximate risk of ovarian cancer in women with a BRCA1 or BRCA2 mutation were most frequently answered incorrectly." (PMID 29246147, 2017).
ovarian carcinoma (continued). "The risk of ovarian cancer in the overall population is about 1.6% while it reaches up to 60% in BRCA1 carriers." (PMID 28182133, 2017). "Our analysis, which focused on functionally disruptive genomic deletions overlapping gene regions, identified a number of loci associated with risk of breast or ovarian cancer for BRCA1 pathogenic variant carriers." (PMID 28145423, 2017). "The presence of peritoneal disease, harboring a primary ovarian cancer, and germline BRCA1/2 mutations were found to significantly predict for RDR in a univariate logistic regression analysis." (PMID 29262651, 2017). "Germline or somatic mutations, copy number loss, and DNA methylation frequently occur in BRCA1/2 in breast and ovarian cancer." (PMID 29383094, 2017). "The prevalence of BRCA1/2 germline mutations in patients with epithelial ovarian cancer is estimated to be about 11–15%." (PMID 28250960, 2017). "In the present study, we have assessed the association between 320 SNPs associated with DAE and breast/ovarian cancer risk among BRCA1 and BRCA2 mutation carriers." (PMID 27796716, 2017). "We describe two patients with advanced ovarian cancer and deleterious BRCA1 mutations who were treated with TH-302, a hypoxia-activated alkylating agent." (PMID 28959512, 2017). "The average cumulative risk of ovarian cancer by age 40 years for BRCA1 mutation carriers has been estimated as 2.8%." (PMID 28376175, 2017). "Approximately 20-25% of ovarian cancers are attributable to germline or somatic BRCA1/2 mutations, resulting in defects in the homologous recombination pathway." (PMID 29137324, 2017). "An increased risk of breast or ovarian cancer is associated with monoallelic mutations in a subset of these genes (BRCA1, BRCA2, BRIP1, PALB2, RAD51C)." (PMID 28874143, 2017). "Her proof of existence of BRCA1 gene and its location has made genetic screening for breast and ovarian cancers possible, saving lives of many people who are at high risk with inherited BRCA1 mutations." (PMID 29162161, 2017). "In December, 2016, US FDA approved rucaparib for the treatment of advanced ovarian cancer patients with general BRCA1/2 mutation and who took at least 2 lines of previous platinum based therapy." (PMID 29214031, 2017). "Here, we have used the multifactorial likelihood method to estimate the probability of pathogenicity of a BRCA1 variant detected in multiple breast/ovarian cancer families from our geographical area (Emilia-Romagna, Italy)." (PMID 28186987, 2017). "Nonetheless, the most well-known factors involved in ovarian cancer susceptibility are mutations in the BRCA1 and BRAC2 genes which are also related to breast cancer susceptibility." (PMID 29262670, 2017). "Among the newly diagnosed ovarian cancers, around 25% of them carry BRCA1/2 mutations from which majority (18%) are germline mutations whereas the remaining (7%) cancers are associated with somatic mutations." (PMID 29214031, 2017). "As a result, this PRS had also a higher discriminatory ability for ovarian cancer for BRCA2 carriers compared with BRCA1 mutation carriers." (PMID 28376175, 2017). "According to the NCCN Ovarian Cancer Guideline Version 1.2016, BRCA1 or BRCA2 mutations are high risk carriers of ovarian cancer." (PMID 29088888, 2017). "According to our gene dependency network, the mutual information of ABAC1 to prognostic risk of ovarian cancer patients is dependent on BRCA1 (The p-value of the edge from BRCA1 to ABCA1 is 0.045)." (PMID 28615526, 2017). "Approximately 7000 new cases of ovarian cancer are diagnosed in the United Kingdom every year, of which 13% to 16% are caused by a germline mutation in either the BRCA1 or the BRCA2 (collectively termed “BRCA”) gene." (PMID 28407998, 2017). "For instance, mutations in tumor suppressor and DNA damage response genes BRCA1/2 leaves the cellular protein depleted or inactive and increases one's risk of breast and ovarian cancer." (PMID 28722656, 2017).
ovarian carcinoma (continued). "Earlier studies investigating the effect of PRS on the absolute risks of breast and ovarian cancer risks of BRCA1 and BRCA2 mutation carriers demonstrated potential for risk stratification." (PMID 28376175, 2017). "Overall, approximately 5%–10% of breast and ovarian cancer cases are due to mutations in the high-penetrance genes BRCA1 and BRCA2 (BRCA)." (PMID 28157161, 2017). "Among the BRCA1/2-negative familial patients from Helsinki and Oulu datasets (N = 1231), eight mutation carriers were identified, and among the 526 ovarian cancer patients from Helsinki, two mutation carriers were identified." (PMID 28702895, 2017). "In the present study, seven deleterious small-range BRCA1/2 mutations were identified in 10% of Colombian breast/ovarian cancer families, including the recurrent BRCA2/1991del4 mutation, which showed a founder origin." (PMID 28680148, 2017). "Hypermethylation of the BRCA1 promoter region is associated with breast and ovarian cancer and analysis of the methylation status of this region is therefore of particular interest." (PMID 28832623, 2017). "This is the first genome-wide CNV association study of BRCA1 pathogenic variant carriers to identify CNVs that are associated with breast and/or ovarian cancer risk, and the first implementation of the retrospective likelihood to CNV data." (PMID 28145423, 2017). "ABAC1 (Entrez ID: 20) mediate the drug- resistance in ovarian cancer, and BRCA1 is the most famous susceptibility gene in ovarian cancer." (PMID 28615526, 2017). "Prospective observational data from the United Kingdom (UK) indicate that the risk of ovarian cancer is much higher among BRCA1 carriers compared with BRCA2 carriers (cumulative risk at age 70 years: 59 versus 17%)." (PMID 28624978, 2017). "It has been reported that germline BRCA1/2 mutations occur in approximately 10 to 20% of patients with invasive epithelial ovarian cancers, and more than 20% of patients with high-grade serous ovarian cancer." (PMID 27690218, 2017). "As genetic testing becomes integrated into the routine management of individuals with ovarian cancer, more women with a germline BRCA1/BRCA2 mutation will be identified." (PMID 28780755, 2017). "Large genomic rearrangements can affect the BRCA1/2 genes, and thus contribute to germline predisposition to familial breast and ovarian cancers." (PMID 29165356, 2017). "The PARP inhibitor olaparib was recently granted Food and Drug Administration (FDA) accelerated approval in patients with advanced BRCA1/2 mutation ovarian cancer." (PMID 28454085, 2017). "SGZ analysis of tumor NGS data indicated high rates of biallelic inactivation for BRCA1/2 mutations, suggesting that loss of BRCA1/2 function is an early event in the progression of ovarian cancer." (PMID 28525389, 2017). "To assess the usefulness of ctDNA in screening for BRCA1/2 mutations, we performed next-generation sequencing in a group of 121 unselected patients diagnosed with ovarian cancer." (PMID 29254167, 2017). "Approximately 25% of patients with ovarian cancer harbor a pathogenic BRCA1/2 mutation that has been associated with favorable responses for targeted therapy with poly (ADP-ribose) polymerase 1 (PARP1) inhibitors compared to wild-type individuals." (PMID 29254167, 2017). "According to current estimates, 5–15% of all ovarian cancers are associated with germinal mutations, with 90–95% of these consisting of mutations within BRCA1/2 genes." (PMID 28182133, 2017). "Preliminary results from the sequencing of an additional series of 50 ovary cancer patients (own data in process) showed three instances of the BRCA1 mutation c.4964_4982delCTGGCCTGACCCCAGAAGA, p.Ser1655_Glu1661?fs." (PMID 28947987, 2017). "Women with heterozygous BRCA1 mutations have a greater risk of developing breast and ovarian cancer in their lifetime." (PMID 27246982, 2016).